ZBTB7B (zinc finger and BTB domain containing 7B)
Description:
Transcription regulator that acts as a key regulator of lineage commitment of immature T-cell precursors. Exerts distinct biological functions in the mammary epithelial cells and T cells in a tissue-specific manner. Necessary and sufficient for commitment of CD4 lineage, while its absence causes CD8 commitment. Development of immature T-cell precursors (thymocytes) to either the CD4 helper or CD8 killer T-cell lineages correlates precisely with their T-cell receptor specificity for major histocompatibility complex class II or class I molecules, respectively. Cross-antagonism between ZBTB7B and CBF complexes are determinative to CD4 versus CD8 cell fate decision. Suppresses RUNX3 expression and imposes CD4+ lineage fate by inducing the SOCS suppressors of cytokine signaling. induces, as a transcriptional activator, SOCS genes expression which represses RUNX3 expression and promotes the CD4+ lineage fate. During CD4 lineage commitment, associates with multiple sites at the CD8 locus, acting as a negative regulator of the CD8 promoter and enhancers by epigenetic silencing through the recruitment of class II histone deacetylases, such as HDAC4 and HDAC5, to these loci. Regulates the development of IL17-producing CD1d-restricted naural killer (NK) T cells. Also functions as an important metabolic regulator in the lactating mammary glands. Critical feed-forward regulator of insulin signaling in mammary gland lactation, directly regulates expression of insulin receptor substrate-1 (IRS-1) and insulin-induced Akt-mTOR-SREBP signaling (By similarity). Transcriptional repressor of the collagen COL1A1 and COL1A2 genes. May also function as a repressor of fibronectin and possibly other extracellular matrix genes. Potent driver of brown fat development, thermogenesis and cold-induced beige fat formation. Recruits the brown fat lncRNA 1 (Blnc1):HNRNPU ribonucleoprotein complex to activate thermogenic gene expression in brown and beige adipocytes (By similarity).
Synonyms: hcKrox; Zfp-67; ZBTB15; ZFP67; ZNF857B; c-Krox; vGAF; ThPOK; CKROX
Tractability: PROTAC: UniProt records ubiquitination sites on it; ubiquitination databases record sites on it; its protein half-life has been measured.
Gene: Protein-coding gene on chromosome 1 (155,002,543 to 155,018,525, forward strand). Ensembl gene ENSG00000160685.
Subcellular location: Nucleus
Subcellular location (Human Protein Atlas): Nucleoplasm
Gene Ontology:
Molecular function: protein binding; sequence-specific double-stranded DNA binding; DNA-binding transcription factor activity, RNA polymerase II-specific; DNA-binding transcription repressor activity; protein homodimerization activity; RNA polymerase II cis-regulatory region sequence-specific DNA binding; cis-regulatory region sequence-specific DNA binding; DNA binding; DNA-binding transcription activator activity, RNA polymerase II-specific; DNA-binding transcription factor activity; histone deacetylase binding; identical protein binding
Biological process: adaptive thermogenesis; ectoderm development; lactation; negative regulation of CD8-positive, alpha-beta T cell differentiation; negative regulation of NK T cell proliferation; NK T cell differentiation; positive regulation of brown fat cell differentiation; positive regulation of CD4-positive, alpha-beta T cell differentiation; positive regulation of cold-induced thermogenesis; positive regulation of gene expression; positive regulation of insulin receptor signaling pathway; positive regulation of interleukin-17 production; positive regulation of SREBP signaling pathway; regulation of transcription by RNA polymerase II; response to insulin; transcription by RNA polymerase II; negative regulation of transcription by RNA polymerase II; positive regulation of transcription by RNA polymerase II
Cellular component: nucleoplasm; nucleus
Genetic constraint (gnomAD): Loss-of-function variants: 7 observed, 26.86 expected, observed/expected ratio (o/e) 0.26, 90% interval 0.15 to 0.49. The upper end of that interval is the gene's LOEUF score, 0.49, which puts it in group 2 of 6, group 1 being the genes least tolerant of losing a copy. Missense variants: 404 observed, 583.45 expected, observed/expected ratio (o/e) 0.69, 90% interval 0.64 to 0.75. Synonymous variants: 203 observed, 236.31 expected, observed/expected ratio (o/e) 0.86, 90% interval 0.76 to 0.96.
Homologues: Orthologues: chimpanzee ZBTB7B (100% identical), macaque ZBTB7B (99% identical), pig ZBTB7B (96% identical), guinea pig ZBTB7B (96% identical), dog ZBTB7B (95% identical), rat Zbtb7b (92% identical), mouse Zbtb7b (92% identical), tropical clawed frog zbtb7b (55% identical), zebrafish zbtb7b (39% identical). Paralogues in human: ZBTB49 (22% identical), BCL6B (19% identical), BCL6 (18% identical), ZBTB21 (16% identical), ZBTB14 (15% identical), ZBTB46 (15% identical), FEZF1 (15% identical), FEZF2 (14% identical), ZBTB12 (14% identical), ZBTB3 (14% identical), ZNF683 (14% identical), NACC2 (13% identical), and 16 more.